MT-TS1 (mitochondrially encoded tRNA-Ser (UCN) 1)
Synonyms: TRNS1; formerly MTTS1
Gene: Mitochondrial transfer RNA gene on chromosome MT (7,446 to 7,514, reverse strand). Ensembl gene ENSG00000210151.
Gene Ontology:
Molecular function: triplet codon-amino acid adaptor activity
Biological process: translation
Gene-disease validity (ClinGen):
ClinGen rates the evidence that MT-TS1 causes each of these diseases.
mitochondrial disease (mitochondrial): Definitive.
Diseases named in the same sentence as MT-TS1 in open-access papers:
MT-TS1 is named in the same sentence as 6 diseases in open-access papers, as found by Europe PMC text mining. Sharing a sentence is not in itself a finding about the gene and the disease. The quoted sentences say what the papers report.
Hearing impairment (2 papers, 2013 to 2017). A decreased magnitude of the sensory perception of sound. "The GJB2, SLC26A4, MT-RNR1 and MT-TS1 genes have been reported as major pathogenic genes in nonsyndromic hearing loss." (PMID 28225033, 2017).
MERRF (1 paper, 2019). A mitochondrial encephalomyopathy characterized clinically by a mixed seizure disorder, myoclonus, progressive ataxia, spasticity, and a mild myopathy. "A family with features of both MERRF and MELAS (MERRF/MELAS overlap syndrome) and a mutation in the gene MTTS1 (transfer RNA, mitochondrial, serine 1) whose members showed bilateral calcification of basal ganglia and cerebral atrophy has been described." (PMID 31267306, 2019).
nonsyndromic hearing loss (1 paper, 2022). "MT-RNR1 is definitively associated with maternally inherited, aminoglycoside-induced hearing loss, and MT-TS1 is definitively associated with mitochondrial nonsyndromic hearing loss." (PMID 35571039, 2022).
MT-TS1 also shares sentences with these, for which no sentence is quoted: Breast Tumor (1 paper); deafness (1); mitochondrial disease (1).